JAK1 (Janus kinase 1)
Diseases named in the same sentence as JAK1 in open-access papers (continued):
Sharing a sentence is not in itself a finding about the gene and the disease.
rheumatoid arthritis (continued). "Filgotinib is a selective JAK1 (Janus kinase) inhibitor, showed efficacy in patients suffering from moderate-to-severe rheumatoid arthritis." (PMID 35300367, 2020). "Upadacitinib is a selective Janus Kinase 1 inhibitor which is being developed for the treatment of several inflammatory diseases including rheumatoid arthritis." (PMID 31654328, 2019). "Upadacitinib is a Janus kinase 1 inhibitor currently being evaluated in phase III rheumatoid arthritis trials." (PMID 28762476, 2018). "The results for a third drug were presented by Frank Brosius, who reported on baricitinib, a Janus kinase 1/2 (JAK1/2) inhibitor that is currently being tested in Phase 3 clinical trials for rheumatoid arthritis." (PMID 27338625, 2016). "JAK1 inhibitors have been demonstrated to possess multiple pharmacological effects and have become therapeutic agents for various diseases, including inflammatory bowel disease, rheumatoid arthritis, autoimmune diseases, and various cancers." (PMID 40746612, 2025). "Furthermore, the most recent development trend, and has great application possibilities is applying JAK1 inhibitors in gastrointestinal diseases, rheumatoid arthritis, and alopecia areata." (PMID 40746612, 2025). "Of the four subtypes of the JAK family (JAK1, JAK2, JAK3, and TYK2), JAK1 is involved in signaling through inflammatory cytokines such as IL-6, and it is known to cause lymphocyte activation and proliferation in rheumatoid arthritis (RA)." (PMID 39944226, 2025). "It is well known that JAK1 inhibitors help to treat atopic dermatitis and rheumatoid arthritis." (PMID 40746612, 2025). "Interestingly, a single case report documented the development of vitiligo - a depigmenting condition - in a rheumatoid arthritis patient treated with Tofacitinib, a JAK1/3 inhibitor." (PMID 39850156, 2024). "So far, the clinical use of JAK1/2 inhibitors is approved in patients suffering from myelofibrosis and rheumatoid arthritis and they are currently in the clinical development targeting several indications such as graft-versus-host-disease, pancreatic cancer, and myeloproliferative diseases." (PMID 39403371, 2024). "Tofacitinib citrate is approved for medical use “to treat adults with moderately to severely active rheumatoid arthritis who have had an inadequate response to or are intolerant of methotrexate”.395–399 Baricitinib, sold under Oluminant, acts as a JAK1 and JAK2 inhibitor." (PMID 36797236, 2023). "While Tofacitinib has not been directly implicated in the regulation of MHC-II, JAK1/2 inhibitor Baricitinib, a drug approved for Rheumatoid arthritis, has been shown to modulate MHC-II on allogenic antigen-presenting cells and prevent graft vs host disease." (PMID 35655783, 2022). "Tofacitinib, a Janus kinase 1 and 3 inhibitor, is used to treat rheumatoid arthritis." (PMID 36559177, 2022). "According to clinical and experimental investigations, rheumatoid arthritis synovial response may be influenced by the JAK1-mediated cytokine (IFN and IL-6) signaling." (PMID 35529449, 2022). "Baricitinib, a selective Janus kinase 1 and 2 inhibitor, has been used to treat rheumatoid arthritis and could reduce the disease severity in patients with livedoid vasculopathy." (PMID 36389811, 2022). "Baricitinib is a Janus kinase 1/2 (JAK1/2) inhibitor used in the treatment of rheumatoid arthritis." (PMID 31360575, 2019). "Hence, Jak1 and Jak2 represent novel therapeutic targets for osteoporosis as well as inflammatory bone diseases including rheumatoid arthritis." (PMID 28708884, 2017). "Furthermore, auranofin, a thioredoxin inhibitor that is used to treat rheumatoid arthritis, inhibits Janus kinase 1 (JAK1)/STAT3 phosphorylation." (PMID 24662938, 2014). "Baricitinib, an oral dual JAK1/2 inhibitor, has proven effective in rheumatoid arthritis (RA) by blocking IL−6/JAK/STAT signaling and reducing structural joint damage." (PMID 41585231, 2025).
rheumatoid arthritis (continued). "Among s-JAKi, tofacitinib, a preferential JAK1/3 inhibitor, has been used in rheumatoid arthritis (RA) since 2012, providing the most extensive long-term safety dataset to date." (PMID 41226626, 2025). "Baricitinib is another selective JAK1/2 inhibitor, which is approved for the treatment of rheumatoid arthritis (RA) and atopic dermatitis (AD)." (PMID 36050429, 2023). "Finally, baricitinib is a small molecule, orally administered, JAK-1 and -2 selective inhibitor used in patients with moderate or severe rheumatoid arthritis or patients with other active disease-modifying antirheumatic drugs with inadequate responses to prior therapies." (PMID 33917093, 2021). "Baricitinib is an oral synthetic inhibitor of the Janus-associated tyrosine kinases JAK1 and JAK2 used in the management of rheumatoid arthritis (RA)." (PMID 34873553, 2021). "Furthermore, clonal deletion of activated T cells was altered and these chronically activated T cells showed persistent IL-6-induced STAT3 and JAK1 phosphorylation indicating that IL-6 signaling in T cells plays a critical role in disease progression of rheumatoid arthritis." (PMID 31694340, 2019). "Upadacitinib is an oral Janus kinase 1 (JAK1) inhibitor being developed for treatment of several inflammatory diseases including rheumatoid arthritis (RA)." (PMID 28762476, 2018). "Upatinib, the only JAK1 inhibitor approved for the treatment of IBD in China, is also indicated for other IMIDs such as atopic dermatitis, rheumatoid arthritis, psoriatic arthritis, and ankylosing spondylitis, with a recommended dosage of 15 mg once daily." (PMID 40143091, 2025). "In July 2021, the FDA issued the Emergency Use Authorization (EUA) for Eli Lilly's Janus kinase 1 and Janus kinase 2 (JAK1 and JAK2) inhibitor baricitinib (Olumiant®) as monotherapy, which is already approved for severe rheumatoid arthritis." (PMID 40371758, 2025). "Tofacitinib is a second-generation selective Janus kinase (JAK) inhibitor targeting the JAK1 enzyme, which is used to treat several autoimmune diseases, including rheumatoid arthritis (RA), psoriatic arthritis, ankylosing spondylitis, idiopathic arthritis, and ulcerative colitis." (PMID 40677425, 2025). "Upadacitinib is an oral, second-generation JAK1 inhibitor currently approved by the FDA and EMA for the treatment of rheumatoid arthritis, axial spondylarthritis, Crohn’s disease (CD), ulcerative colitis, and atopic dermatitis in adult patients." (PMID 40507644, 2025). "Filgotinib, administred at 200 mg once daily, is a selective, ATP-competitive JAK1 inhibitor approved in September 2020 by the EMA and in Japan for treating moderate to severe rheumatoid arthritis in adults." (PMID 41438753, 2025). "JAK inhibitors proven to be potent anti-inflammatory drugs include tofacitinib (inhibiting JAK1/2/3), baricitinib (inhibiting JAK1/2), and upadacitinib (selectively inhibiting JAK1), all of which have received FDA approval for treating rheumatoid arthritis." (PMID 40328798, 2025). "JAK1/2 inhibition of AP by baricitinib further supports that IFN-γ is essential for BTECs and is currently investigated as treatment for rheumatoid arthritis." (PMID 40107244, 2025). "Tofacitinib is a JAK1/3 inhibitor, with less efficacy vs. JAK2 and TYK2, and it is approved for the treatment of rheumatoid arthritis, psoriatic arthritis and ulcerative colitis." (PMID 38665231, 2024). "Baricitinib is an inhibitor of JAK1/2, with moderate activity vs. TYK2, with an indication for the treatment of rheumatoid arthritis." (PMID 38665231, 2024). "On the other hand, Tofacitinib inhibits JAK1, JAK2, JAK3 and is approved by the Food and Drug Administration (FDA) for treating rheumatoid arthritis (RA), psoriatic arthritis and ulcerative colitis." (PMID 38920670, 2024). "Baricitinib inhibits both JAK1 and JAK2 and can be used to treat patients with rheumatoid arthritis." (PMID 38318160, 2024).
rheumatoid arthritis (continued). "Baricitinib is an oral, specific, and reversible JAK1 and JAK2 inhibitor authorized for the management of rheumatoid arthritis, atopic dermatitis, and severe alopecia areata in many countries." (PMID 39525758, 2024). "In another study, baricitinib, an inhibitor with selectivity for JAK1/JAK2, currently approved for the treatment of rheumatoid arthritis, was seen to allow treated patients to significantly reduce steroid use." (PMID 38334659, 2024). "It is an oral inhibitor of the enzymes JAK1, JAK2, and JAK3, which was approved in 2012 for the treatment of moderate to severe rheumatoid arthritis (RA)." (PMID 39770590, 2024). "Tofacitinib is an oral JAK-1 and JAK-3 inhibitor that has been approved for the treatment of rheumatoid arthritis and ulcerative colitis, plaque psoriasis, atopic dermatitis, vitiligo, and alopecia areata." (PMID 38397117, 2024). "Baricitinib is a JAK1 and JAK2 inhibitor approved for treating active rheumatoid arthritis and atopic dermatitis." (PMID 39525758, 2024). "Baricitinib, a selective JAK1 and JAK2 inhibitor, has been approved for treatment of active rheumatoid arthritis and reported in treatment of some other autoimmune diseases including systemic lupus erythematosus." (PMID 36793118, 2023). "Tofacitinib is an oral inhibitor of Janus kinase 1 (JAK1) enzyme and of Janus kinase 3 (JAK 3), used in combination with methotrexate for the management of active rheumatoid arthritis." (PMID 35203646, 2022). "Baricitinib is a selective Janus kinase 1 (JAK1) and 2 (JAK2) inhibitor used for the treatment of rheumatoid arthritis." (PMID 36389811, 2022). "Upadacitinib, an oral reversible JAK inhibitor with greater inhibitory potency for JAK1 than JAK2, JAK3, and TYK2, has been approved by the U.S. FDA for treating AD, rheumatoid arthritis, and psoriatic arthritis." (PMID 36569854, 2022). "Baricitinib (Olumiant), a small molecule JAK1/JAK2 inhibitor, is approved for the treatment of rheumatoid arthritis (RA) and has been proven to reduce lung fibrosis and inflammation in patients with RA-associated ILD (RA-ILD)." (PMID 35626663, 2022). "Tofacitinib, an effective oral JAK2/1/3 inhibitor, and baricitinib, a selective JAK1/JAK2 inhibitor, were approved by the FDA for the treatment of rheumatoid arthritis (RA) and ulcerative colitis(UC)." (PMID 34335579, 2021). "Baricitinib is a selective, efficient and safe janus kinase 1 (JAK1) and 2 (JAK2) inhibitor approved for usage in rheumatoid arthritis treatment." (PMID 34063964, 2021). "In the same year, the U.S. Food and Drug Administration (FDA) approved a second JAK inhibitor: tofacitinib (JAK1 and JAK3) for the treatment of rheumatoid arthritis." (PMID 34532638, 2021). "Tofacitinib is already approved as a JAK1 and JAK3 inhibitor for the treatment of rheumatoid arthritis, psoriatic arthritis, and ulcerative colitis." (PMID 34532638, 2021). "Baricitinib is a JAK1 and JAK2 inhibitor that is used in rheumatology for the treatment of rheumatoid arthritis, but here usually in combination with methotrexate." (PMID 34532638, 2021). "Tofacitinib (TOF) inhibits JAK1/JAK3 and has been proven effective in rheumatoid arthritis (RA), psoriatic arthritis, ulcerative colitis, and a new therapeutic option in systemic lupus." (PMID 34313812, 2021). "The efficacy of Baricitinib (LY3009104), a reversible inhibitor of Janus kinase 1 (JAK1) and JAK2 currently used in rheumatoid arthritis, is currently being evaluated in an ongoing, placebo controlled phase 2 trial (NCT03742973)." (PMID 33919600, 2021). "Upadacitinib (anti-JAK1), fedratinib (anti-JAK2), and oclacitinib (anti-JAK1) were approved by FDA for rheumatoid arthritis, myelofibrosis, and dermatitis, respectively." (PMID 32527304, 2020). "Baricitinib and ruxolitinib, both targeting JAK1 and JAK2 which are the dominant kinases downstream of IL-6, have been approved for the treatment of myelofibrosis and rheumatoid arthritis, respectively." (PMID 33384605, 2020).
rheumatoid arthritis (continued). "Ruxolitinib is a JAK1/JAK2 inhibitor approved by the Food and Drug Administration (FDA) for psoriasis, myelofibrosis, and rheumatoid arthritis." (PMID 32527304, 2020). "In myeloproliferative neoplasms the JAK-STAT signaling pathway can be inhibited with the JAK1/JAK2 inhibitor ruxolitinib and in rheumatoid arthritis with less selective JAK inhibitors such as tofacitinib and baricitinib." (PMID 32188095, 2020). "Peficitinib is a JAK1/2/3 and TYK2 inhibitor, approved in Japan in 2019 for rheumatoid arthritis after Phase III clinical trials demonstrated a reduction in symptoms and minimal toxicity compared to placebo in clinical trials." (PMID 33521321, 2020). "JAK1 inhibitors, for example, small molecule tofacitinib that inhibits JAK1 and JAK3, are used for treatment of rheumatoid arthritis and are currently tested in other immunological disorders, such as psoriasis and inflammatory bowel disease." (PMID 28008925, 2016). "In a recent report, gain of ≤ 10% body weight was observed in six out of seven rheumatoid arthritis patients treated with baricitinib but not with tofacitinib, a JAK1/3 inhibitor." (PMID 39564906, 2025). "The patient with rheumatoid nodules for the longest duration did not experience improvement in rheumatoid nodules on tofacitinib, but noted resolution while on upadacitinib, possibly due to stronger JAK1 inhibition." (PMID 40290798, 2025). "Tofacitinib, which inhibits JAK1, JAK3, and to a slightly lesser extent JAK2, therefore may function to reduce or inhibit inflammatory pathways that lead to rheumatoid nodule formation." (PMID 39070924, 2024). "JAK1/2 inhibitor baricitinib is a marketed drug for the treatment of rheumatoid arthritis, but its role in pulmonary fibrosis has not been reported." (PMID 36903446, 2023). "Moreover, several small molecules with JAK1 and JAK2 inhibitory activity have also provided therapeutic benefits in the treatment of rheumatoid arthritis, psoriasis, and pruritis." (PMID 35631587, 2022). "Baricitinib, a selective and reversible inhibitor of the Janus kinases JAK1 and JAK2, previously approved for the treatment of rheumatoid arthritis, has been recently licensed for the treatment of severe Coronavirus disease 2019 (COVID-19) (COVID-19 Treatment Guidelines Panel." (PMID 36140425, 2022). "In addition, “bone inflammation disease” and “rheumatoid arthritis” ontologies were highly enriched in C3 regions, confirming that C3 regions represent an RA signature, for example, IL-1B and JAK1, which are essential for proinflammatory signal transduction and upregulated in RA patients." (PMID 33863328, 2021). "For example in a study of rheumatoid arthritis monocytes, we observed that JAK1 expression fit this pattern, in patients only and not in controls." (PMID 34847931, 2021). "Another JAK1-selective blocking agent filgotinib also did not result in anemia in rheumatoid arthritis patients." (PMID 33343569, 2020). "Two long term extension studies of tofacitinib, (a JAK1/JAK3 inhibitor with a nearly identical target profile to that of oclacitinib), in patients with rheumatoid arthritis found that fewer than 5% experienced neutropenia of any degree, and most were mild in severity." (PMID 31409327, 2019). "Recent positive results seen in rheumatoid arthritis for tofacitinib, a JAK1/3 (plus some JAK2 activity) inhibitor, and baricitinib, a JAK1/2 inhibitor, have for the first time offered the promise of biologic-like efficacy with an oral small molecule inhibitor." (PMID 29938195, 2018). "Tofacitinib, with specificity for JAK1 and JAK3, reduces IL-23 triggered IL-17A secretion from T cells of rheumatoid arthritis (RA) and psoriatric arthritis (PSA) patients in vitro, and was the first JAK inhibitor to be licensed for treatment of RA in the United States15,16." (PMID 30353145, 2018).
rheumatoid arthritis (continued). "Tofacitinib is a potent inhibitor of JAK1 and JAK3 and currently approved for the treatment of rheumatoid arthritis (RA), has demonstrated effectiveness in the treatment of psoriasis in phase III clinical trials, and is currently tested as immunomodulator for organ transplantation." (PMID 26983628, 2016). "While a pan-JAK inhibitor has been shown to increase the risk of thromboembolic and major cardiovascular events (MACE), especially in elderly patients with rheumatoid arthritis, UPA may potentially be a better therapeutic option for elderly IBD patients owing to its selective effect on JAK1." (PMID 41546037, 2026). "Similarly, anti-TNFα therapy has been shown to reverse compromised Treg function in rheumatoid arthritis, and tyrosine kinase 2 (TYK2) inhibitors might prove superior to Janus kinase 1 (JAK1) inhibitors in the treatment of PsoA regarding Treg function." (PMID 40806470, 2025). "Tofacitinib, which primarily inhibits JAK1 and JAK3 with partial JAK2 inhibition, is approved for conditions like rheumatoid arthritis (RA) and ulcerative colitis (UC), but has emerging applications in dermatologic diseases." (PMID 41235382, 2025). "Using KO simulations, we identified NFkB, JAK1/JAK2, and ERK1/Notch1 as potential targets that could selectively suppress proinflammatory macrophages and GSK3B as a promising target that could promote anti-inflammatory macrophages in rheumatoid arthritis." (PMID 38272919, 2024). "Baricitinib is an oral selective inhibitor of JAK1 and JAK2, which has demonstrated significant efficacy in rheumatoid arthritis (RA) patients." (PMID 39430463, 2024). "Filgotinib, a janus kinase 1 (JAK1) inhibitor, is used in the treatment of rheumatoid arthritis (RA)." (PMID 39253319, 2024). "Filgotinib, a JAK1/JAK2 inhibitor, has been administered to patients with rheumatoid arthritis (RA) since 2016." (PMID 39684719, 2024). "Tofacitinib (Xeljanz®) is a potent, selective JAK inhibitor that preferentially inhibits JAK1 and JAK3 used for the treatment of moderate to severe active rheumatoid arthritis (RA), Tofacitinib had promising in vitro activity on MM cells." (PMID 36311273, 2022). "Baricitinib is an oral synthetic Janus Kinase inhibitor that inhibits JAK1 and JAK2, and the new kid on the block in the treatment of rheumatoid arthritis (RA)." (PMID 34873553, 2021). "The baseline risk of HZ in rheumatoid arthritis is 1.5–2-fold higher compared to the general population, and the incidence of HZ reported with tofacitinib, which preferentially inhibits JAK1, JAK2, and JAK3, is double that reported in RA." (PMID 32974356, 2020). "Baricitinib, an oral-administrated selective inhibitor of the JAK1 and JAK2, is recently approved for rheumatoid arthritis (RA) treatment." (PMID 30777075, 2019). "Baricitinib was approved by the U.S. FDA as a selective JAK1 and JAK2 inhibitor for the indications of rheumatoid arthritis and Coronavirus Disease 2019 (COVID-19) but not yet for atopic dermatitis." (PMID 36569854, 2022).